IL6 (interleukin 6)
Diseases named in the same sentence as IL6 in open-access papers (continued):
Sharing a sentence is not in itself a finding about the gene and the disease.
COVID-19 (continued). "IL-6 levels were increased on day 2 in all animals in this group relative to baseline, but two of the five animals had increases that were much greater than the others (>35 pg/mL and >10x over baseline), reaching levels reported for severe cases of COVID-19 in humans." (PMID 34424943, 2021). "Therefore, upregulation of IL6 and NFkB genes may contribute to the inflammatory symptoms observed in severe COVID-19 patients." (PMID 33796130, 2021). "In addition, subclinical inflammatory responses, especially elevations in both IL-1β and IL-6, have been shown to occur prior to the onset of T2DM, which further suggests that COVID-19 may increase the risk of new-onset diabetes." (PMID 34867819, 2021). "Further data from ongoing RCTs are needed to correctly assess the benefits of using IL-6 inhibitors to manage COVID-19, including the timing and route of administration and different patient populations, which will provide a more detailed understanding of whether this therapy is effective." (PMID 34959657, 2021). "Therefore, hyperglycemia may induce a burst of IL-6 to participate in the progress of cytokine storm to aggravate COVID-19 symptoms." (PMID 33480978, 2021). "In addition to IL-6, the elevation of three other proinflammatory and pulmonary injury-associated proteins, TNFSF14, EN-RAGE and oncostatin-M, were found in strong positive correlation with the severity of COVID-19." (PMID 33912590, 2021). "High IL-6 and viral RNAaemia, which would reflect hyperinflammation and viral overload as its trigger, may contribute to accurate prediction of clinical outcomes based on pathophysiological understanding of future deterioration of COVID-19." (PMID 34379684, 2021). "Indeed, CART algorithm clearly indicated that IL-6 discriminated controls and COVID-19 patients." (PMID 34675240, 2021). "The spectrum of drugs to treat COVID-19 is also rapidly evolving, including antivirals (remdesivir, favipiravir), antimalarials (chloroquine, hydroxychloroquine), corticosteroids, anti-cytokine agents (IL-6 inhibitors), monoclonal antibodies and immunoglobulin therapy (convalescent plasma)." (PMID 35053169, 2021). "The dataset did not include Interleukin 6 (IL-6) or D-Dimer levels, which might be associated with COVID-19 severity and mortality." (PMID 33446135, 2021). "Therefore, drugs targeting the IL-6/JAK/STAT pathway with anticancer effects may be repurposed for the treatment of COVID-19, saving invaluable time and allowing timely delivery of care." (PMID 34001144, 2021). "Therefore, IL-6 can be used as a prognostic indicator of COVID-19." (PMID 34205852, 2021). "Quercetin, ursolic acid, luteolin, and rutin could inhibit COVID-19 by down-regulating IL-6." (PMID 33146673, 2021). "In addition, diabetes may cause a chronic inflammatory state, elevating the levels of pro-inflammatory cytokines, such as interleukin-1 (IL-1) and IL-6, and further aggravate cytokine storms in some patients with COVID-19." (PMID 33771154, 2021). "However, the reported levels of cytokines, including IL-6, in patients with COVID-19 were profoundly lower than those typically observed in non-COVID-19 ARDS cases and in sepsis, thus casting doubt on the role of cytokine storms in the progression to ARDS with COVID-19." (PMID 34616852, 2021). "Furthermore, the upregulation of IL-6 in fatal cases of COVID-19 indicates that mortality may be driven by hyperinflammation." (PMID 33853637, 2021). "Therefore and irrespective of the concept that IL-6 is the cause of severe cases of COVID-19 or a reliable biomarker for COVID-19, periodontitis could modify the level of IL-6 in COVID-19 patients." (PMID 33975613, 2021). "In addition, high levels of IL-6 were observed in patients with COVID-19 and might serve as a predictive biomarker for disease severity." (PMID 33420963, 2021). "Finally, we tested the hypothesis that elevated IL-1β and IL-6 transcriptional activity in blood could predict clinical outcome in COVID-19." (PMID 33319166, 2021).
COVID-19 (continued). "It has been hypothesized that inhibition of cytokine signaling could impair clearance of SARS-CoV-2, and result in worse outcomes such as secondary infections; this has been previously observed in the treatment of influenza and subsequent to the use of IL-6 inhibitors in COVID-19 patients." (PMID 34341776, 2021). "In addition to fibrinogen synthesis and platelet production, IL-6 does not cause fibrinolysis that causes coagulopathy in COVID-19 patients." (PMID 34829418, 2021). "Severe COVID-19 is characterized by a marked hyperinflammatory response resulting in a cytokine storm, with dysregulated production of proinflammatory cytokines (e.g., IL-1β and IL-6), resulting in significant lymphopenia, C-reactive protein increase, and a profound vascular dysfunction." (PMID 34903264, 2021). "Similarly, in a meta-analysis of transcriptomic data, the upregulation of the monocytic compartment in severe COVID-19, was dependent on the cytokines IL-6 and IL-10, and was characterized by broadly immunosuppressive properties and decreased responsiveness to stimulation." (PMID 34220859, 2021). "Consequently, the Society for Immunotherapy of Cancer has suggested that anti-IL-6 drugs may be useful in COVID-19 treatment." (PMID 33510335, 2021). "In this case series, critically ill patients with COVID-19 with severe acute respiratory failure refractory to prone positioning and hypercytokinemia who received adjuvant treatment with cytokine hemoadsorption showed a significant reduction in IL-6 plasma levels and other inflammatory biomarkers." (PMID 35083241, 2021). "Therefore, higher circulating levels of IL-6 in patients with more intense headache could point out a potential trigger role of IL-6 in COVID-19 headache." (PMID 34384355, 2021). "Moreover, body temperature before admission, sustained fever status, the length of hospital stay, higher WBC counts, elevated levels of AST, CREA and IL-6, and lymphopenia on admission tended to be independent factors for predicting disease severity in COVID-19 patients." (PMID 34123873, 2021). "Tocilizumab may improve the prognosis of severe COVID-19 patients with high levels of IL-6." (PMID 33731184, 2021). "Importantly, IL-6 was found to be elevated in the serum of patients with COVID-19." (PMID 34001144, 2021). "In addition, the high cytokine levels secreted from hypertrophic fat cells into the bloodstream, including IL-6, counteract the termination of the anti-viral immune response in the lungs of and thereby promote a cytokine storm in COVID-19 patients with a severe disease development." (PMID 33824998, 2021). "Moreover, serum IL-6 level is a known predictive biomarker of COVID-19 severity." (PMID 34711897, 2021). "Moreover, the increment of pro-inflammatory cytokines including interlukin-6 (IL-6) that is usually observed in COVID-19 might lead to further lymphocyte reduction." (PMID 34855832, 2021). "However, IL-6 levels in COVID-19 patients are lower than the median values typically reported in ARDS17,18, and other unidentified determinants may define COVID-19 severity." (PMID 34667241, 2021). "Moreover, the same cytokine (i.e., IL-6) is also seen to be increased in COVID-19 patients." (PMID 33981235, 2021). "In addition, BAL may have a prognostic role; indeed, the identification of an extensive alveolitis in COVID-19 patients, particularly in the presence of high levels of IL6 and IL8, correlates with the severity of the disease and predict clinical outcomes." (PMID 34679633, 2021). "Additionally, the Ang2-AT1R pathway mediates the conversion of a soluble form of IL-6 and is vasoconstrictive and pro-fibrotic, playing an essential role in the pathogenesis of COVID-19." (PMID 33935717, 2021). "In addition, our study also indicated that tocilizumab, a monoclonal antibody against the IL-6 receptor, may improve the prognosis of severe COVID-19 patients with the high level of IL-6." (PMID 33731184, 2021).
COVID-19 (continued). "Finally, we analyzed the correlation between the indicators related to the reduction of Ca2+ (including serum Ca2+, PCT and calcitonin), coagulation function-related indicators (including D-dimer and PFDP), and inflammation indicators (ESR, CRP, and IL-6) in COVID-19 patients." (PMID 34222271, 2021). "Thus, therapies targeting IL-6 and IL-10 could be investigated as a means for improving NK cell antiviral immunity, especially in severe cases of COVID-19." (PMID 35062250, 2021). "Also, IL-6, a proinflammatory mediator, is elevated in COVID-19 and induces CNS immune responses." (PMID 33981305, 2021). "However, IL-6 was surprisingly lower in COVID-19 compared to ARDS." (PMID 34573092, 2021). "Whether the cytokine storm and the IL-6 increase in COVID-19 are transient or sustained processes remains unclear, but monitoring these biomarkers may be important, as they may be predictive of complications in long-term COVID-19." (PMID 34151246, 2021). "According to other studies, doxycycline may delay COVID-19 progression via anti-inflammatory activities, including regulating the NFκB pathway and inhibition of proinflammatory cytokine levels (IL-6, IL-1β, TNFα), measured during ARDS in severely ill COVID-19 patients." (PMID 34372498, 2021). "Specifically, we found that the expression of genes encoding proinflammatory cytokines (IL12B, IL15, IL6, IL12A and IL1B) and chemokines (CXCL9, CXCL11 and CXCL10) was broadly increased in COVID-19 patients and speculate that other viral infections may also induce expression of these genes." (PMID 33780352, 2021). "Authors suggested that mast cells may play an important role in triggering the systemic cytokine storm associated with severe COVID-19 because of their production of various mediators, including IL-4 and IL-6, two cytokines involved in COVID-19 disease pathogenesis." (PMID 34685733, 2021). "Moreover, IL-6 may promote the development of ARDS in COVID-19 patients, and an increased IL-6 level may be a sign of more aggravated disease." (PMID 33967617, 2021). "The severity and the prolonged course of COVID-19 in these patients might be caused by persisting systemic inflammation reflected in fever and elevated C-reactive protein (CRP) as well as interleukin-6 (IL-6)." (PMID 33500431, 2021). "For example, TNF-α and interleukin (IL)-6 impair mitochondrial oxidative phosphorylation and coupled ATP production and trigger the production of mitochondrial ROS in the cell, leading to mitochondrial dysfunction, which has been found expressed in patients with COVID-19." (PMID 34204362, 2021). "Collective data indicate that anti-inflammatory cytokines, including IL-10, are likely produced to limit the cytokine storm observed following SARS-CoV-2 infection; however, IL-10 fails to achieve this, as high levels of IL-6 in conjunction with IL-10 are associated with severe cases of COVID-19." (PMID 34251989, 2021). "They authors of the study suggested that circulating lymphocytes, CRP, procalcitonin, IL-6, and viral load could serve as predictors for disease typing and guide classification of COVID-19 patients, and that circulating lymphocytes was the most reliable and sensitive predictor biomarker." (PMID 35174189, 2021). "IL-6, IL-8, IL-10, and Ts cell might be independent predictors for the poor outcome of COVID-19." (PMID 33542929, 2021). "A significant difference was observed in the levels of IL-6 and IL-7 between severe and mild patients at 1–3 days and 4–6 days since onset (p < 0.05 or p < 0.01), which is in accordance with the published literature about IL-6 as a severity predictor of COVID-19." (PMID 34925252, 2021). "Thus, we further demonstrated that IL-6 blockade might constitute a novel therapeutic strategy for severe patients with COVID-19." (PMID 34970527, 2021). "The drug could prevent the expression of IL-6 in COVID-19 patients." (PMID 34179072, 2021).
COVID-19 (continued). "Moreover, symptomatic children with COVID-19 were found to have higher viral load, lower total lymphocyte count, lower lymphocyte subsets, and elevated interleukin 6 (IL-6), IL-10, tumor necrosis factor-alpha (TNF-α), and interferon-gamma (IFN-γ) levels compared with asymptomatic patients." (PMID 34975908, 2021). "However, recent research discoveries revealed that both IL-6 and IL-6R blockade may reduce the benefit in patients with COVID-19." (PMID 33404925, 2021). "However, the standardization of dose and timing for administration may still represent a valuable step to ponder the role of IL-6 signaling into the disease’s pathophysiology, and thus in tocilizumab’s efficacy for the treatment of COVID-19." (PMID 34611251, 2021). "Drugs targeting IL-6/JAK/STAT signaling may assist in the treatment of COVID-19." (PMID 33995078, 2021). "Inhibition of ACE in COVID-19 patients with hypertension reported reduced disease severity with downregulation of IL-6 and higher T cell numbers, suggesting the exaggerated activation of Ang-II/AT1R axis may contribute towards the uncontrolled cytokine response leading to ALD." (PMID 33632295, 2021). "In addition, IL-2R and IL-6 markedly decreased in cancer patients who recovered from COVID-19." (PMID 33735106, 2021). "Likewise, a case was reported wherein anti-SARS-CoV-2 IgM antibodies and IL-6 levels were noted to be comparatively higher than the normal neonates indicating the likelihood of transplacental transmigration of virus from COVID-19 positive mother to the neonate." (PMID 34595136, 2021). "Thus, for example, IL-6 and interleukin 1RA (IL-1RA) increases were similar in some studies of influenza-associated ALI/ARDS patients and COVID-19 ARDS patients, but the interferon activity was significantly depressed in COVID-19 patients compared with influenza ARDS patients." (PMID 33672738, 2021). "However, according to the fact that IL-6 plays a crucial role in cytokine storms and the latter dramatically worsen symptoms of COVID-19 patients, IL-6 and its receptors may be good therapeutic targets." (PMID 37287491, 2021). "Thus, the blockage of IL-6 activity might play a role in mitigating the inflammatory response and, subsequently, it might improve clinical outcomes in patients with COVID-19." (PMID 34884178, 2021). "Notably, it is reported that IL-38 increased significantly in influenza and COVID-19 patients and may function as a suppressor cytokine that inhibits IL-1, IL-6 and TNF-α in COVID patients." (PMID 34054828, 2021). "Because IL-6 trans signaling and IL-1β play vital roles in both COVID-19 and HF, their inhibitors may be effective and novel treatments to prevent the progression of HF in patients with COVID-19." (PMID 33404925, 2021). "Although the cellular source of these cytokines was not determined during many virus infections (e.g., the cellular source of elevated IL-6 in COVID-19 patients), the synergic action of these proinflammatory cytokines may inhibit lymphopoiesis in the bone marrow." (PMID 34578457, 2021). "For instance, in wave 2, the loss of IL-6 augmentation in severe COVID-19 may be explained with the treatment approach, definitely not based on tocilizumab administration." (PMID 34675240, 2021). "Therefore, MMP inhibition by TCs might explain the beneficial role of such agents in controlling COVID-19–induced ARDS as evident by the reduction of IL-6 serum levels." (PMID 33967777, 2021). "However, IL-6 and IL-10 showed a marked increase by COVID-19 severity." (PMID 34460840, 2021). "In the respective observational time period of our cases, the mortality of mechanically ventilated COVID-19 patients in ICUs in Germany remained at 50% across age groups even with introduction of additional therapeutic measures like early corticosteroids/dexamethasone or IL-6 blockade." (PMID 34565332, 2021).
COVID-19 (continued). "The basic risk factors for cytokine storms in COVID-19 patients include male gender, lactate dehydrogenase level, age over 40 years, positive test result for replicative SARS-CoV-2 RNA, absolute lymphocyte count, D-dimer and ferritin levels, dynamics in the NEWS score, and plasma IL-6 concentration." (PMID 34858403, 2021). "In COVID-19, metabolic status changes, namely, the increased levels of circulating glucose and FFA, high levels of oxidative stress, and SIR (including IL-6, CRP), that are characteristic of pathologies associated with insulin resistance and correlates with the severity of the disease, may occur." (PMID 34299201, 2021). "Therefore, IL-6 stands as a common biomarker for AD and COVID-19." (PMID 33078369, 2021). "Similarly, increases in IL-6, in the absence of increases in IL-10, have been associated with disease progression in a nonhuman primate model of COVID-19." (PMID 34424943, 2021). "Interestingly, G-CSF, IL-1β and IL-6 were still elevated in post-COVID-19 compared to HC." (PMID 34572439, 2021). "Consequently, IL-6 inhibitors should be cautiously used to manage COVID-19." (PMID 34576053, 2021). "IL-6 biological activities and the positive effect of SARS-CoV-2 on its production made us speculate that the underlying event implicated in the development of disseminated KS in our patient could be COVID-19." (PMID 34930492, 2021). "The pathophysiological characteristics of COVID-19 are severe inflammation and chemokine storms, which may be the driving factors behind acute lung injury and acute respiratory distress syndrome, as well as the main consequence of IL-6 elevation." (PMID 33557779, 2021). "As CRS is one of the hallmarks of critically ill COVID-19 patients, it is plausible that administration of immune-suppressive medications such as IL-1 or IL-6 blockade with therapeutic antibodies and antioxidative agents may also mitigate the risk of CSVD in COVID-19 patients." (PMID 34176095, 2021). "Serum levels of IL-6 and ferritin, as inflammatory biomarkers, are reported to be significantly increased in COVID-19 non-survivors compared to survivors, while patients with severe COVID-19 have been reported to have higher neutrophil and lower lymphocyte counts." (PMID 34829345, 2021). "Similarly to SARS, inflammation plays an important role in the pathophysiology of COVID-19, and patients with severe disease may have high serum concentrations of inflammatory markers such as IL-6, TNF, C-reactive protein (CRP), and D-dimer." (PMID 34960790, 2021). "In the present meta-analysis, numerous inflammatory biomarkers (ESR, CRP, PCT, ferritin, and IL-6) were higher in deceased patients than in survivors, providing further evidence for the presence of a cytokine storm that can contribute to the fatal outcome of COVID-19 patients." (PMID 34238232, 2021). "The NR3C2 activity of corticosteroids, and indeed the other targets including progesterone receptors, may well be beneficial for other aspects of COVID-19 severity mitigation beyond the IL-6 cytokine nexus that was explored in this study via clinical-omics triangulation." (PMID 33723251, 2021). "Elevated IL-6 at admission may be a predictor biomarker of ICU-AW in COVID-19." (PMID 33755815, 2021). "Likewise, sarilumab, another IL-6 antibody, is also under trials for the treatment of COVID-19." (PMID 34721573, 2021). "Tocilizumab, an immunosuppressive drug blocking IL-6 receptors, has shown a seemingly positive effect in patients with COVID-19; however, because of adverse effects, new candidate molecules that are more effective and/or act on the level of transcription or translation of IL-6 are needed." (PMID 33467724, 2021). "IL-6 blockage may contribute to counteracting severe and critical outcome in COVID-19 patients." (PMID 34575388, 2021). "In this study, IL-6, TNFα and IL-8 might be potential targets for immunotherapy of COVID-19." (PMID 33349241, 2020).